BST2 (bone marrow stromal cell antigen 2)
Diseases named in the same sentence as BST2 in open-access papers (continued):
Sharing a sentence is not in itself a finding about the gene and the disease.
acute liver failure (1 paper, 2017). Rapid deterioration of liver function causing encephalopathy and coagulopathy. "In HEV associated acute liver failure, there was an overall increase in the intensity of anti-BST2 (Tetherin) staining in hepatocytes." (PMID 29091957, 2017). "Immunohistochemistry in histologically normal liver and HEV associated acute liver failure revealed BST2 overexpression in HEV infected hepatocytes and a dominant canalicular BST2 distribution in normal liver in addition to the cytoplasmic localisation reported in literature." (PMID 29091957, 2017). "Our IHC studies showed distribution of BST2 (Tetherin) on bile canaliculi and an overexpression in HEV infected hepatocytes of acute liver failure patients." (PMID 29091957, 2017).
adenoma (1 paper, 2024). A neoplasm arising from the epithelium. "Top over-represented EV proteins from the adenoma ZMTH3 were mainly related to immune response (ISG15, BST2, IFI44), while top under-represented proteins identified in the adenoma ZMTH3 EVs were associated with migratory and adhesion activity (MXRA8, TNN, SERPINB8), similar to the WCLs." (PMID 39462388, 2024).
age-related macular degeneration (1 paper, 2019). Age-related loss of vision in the central portion of the retina (macula), secondary to retinal degeneration. "In another study, treatment of retinal pigment epithelium (RPE) cells with amyloid-β1-40, a known inflammatory trigger in Age-related macular degeneration (AMD) caused a significant induction of inflammatory genes such as BST2, STAT1, RSAD2, MX2, OAS1&2, IFNL44 and LXN43." (PMID 30914656, 2019).
anemia (1 paper, 2019). A reduction in the number of red blood cells, the amount of hemoglobin, and/or the volume of packed red blood cells. "MYC+RUNX2-DKO leukemic cells were transplantable in secondary recipient mice with the same CD11b−CD11cmid/+B220+Bst2+ immunophenotype, and recipient mice died earlier at 2 weeks post-transplantation (the median survival, 23 days) due to severe anemia and thrombocytopenia." (PMID 30971697, 2019).
arboviral diseases (1 paper, 2023). "Expression of BISPR, BST2, and OASL in other arboviral diseases." (PMID 37922302, 2023).
asthma (1 paper, 2014). "We assessed the activity of a novel protein drug designated ISU201, the extracellular domain of the human cell surface protein BST2, stabilised by fusion with the Fc region of IgG, in mouse models of mild chronic asthma and an acute exacerbation of asthma." (PMID 24594933, 2014).
cardiomyopathies (1 paper, 2023). "ADGRD1 and BST2 have not been previously associated with cardiomyopathies and/or heart failure and represent targets for elucidating pathophysiological mechanisms and future drug development." (PMID 36950336, 2023).
Chagas disease (1 paper, 2024). A parasitic infection caused by Trypanosoma cruzi. "Our study points to IFI204/IFI16 and BST2 as potential Chagas disease targets and SLAMF1 as their inhibitor through some unknown mechanism." (PMID 39000601, 2024).
chondroblastoma (1 paper, 2009). A benign, chondroid-producing, well-circumscribed, lytic neoplasm usually arising from the epiphysis of long bones. "The meta-analysis showed that only the gene BST2 (CDNA FLJ59809 complete cds, highly similar to Bone marrow stromal antigen 2) (accession number: NM_004335) had significantly higher expression in growth plates versus chondroblastomas (adjusted p = 0.008)." (PMID 19903358, 2009).
coeliac disease (1 paper, 2008). "In this study, genes for growth arrest-specific 6 (GAS6) and bone marrow stromal cell antigen 2 (BST2) were found to be up-regulated in active coeliac disease, and both have previously been reported to induce cell proliferation." (PMID 18691394, 2008).
colitis (1 paper, 2024). Inflammation of the colon. "Of note, Bst2, Socs1, and Usp18 showed significant induction in B. fragilis–monocolonized mice compared with GF mice during experimental colitis." (PMID 38085267, 2024).
colorectal tumors (1 paper, 2017). "Similarly, previous studies have also found an association between higher expression levels of FER1L4 and tumor suppressor functions, and between up-regulation of the miR-135b and BST2 genes and both metastatic and poor prognosis colorectal tumors." (PMID 29296198, 2017).
demyelinating disease (1 paper, 2026). A broad group of disorders that affect the myelin sheaths that cover the neurons. "Particularly, in EAE mouse models, specific knockout of BST2 in SCs delays the progression of demyelinating disease." (PMID 41391004, 2026).
demyelination (1 paper, 2026). "We identified BST2 as the most significantly upregulated gene in aged cochlear SCs, with validation at both mRNA and protein levels that correlated strongly with hearing threshold increases and demyelination severity." (PMID 41391004, 2026).
depression (1 paper, 2024). "Notably, a substantial number of upregulated genes associated with depression were identified, such as Ctss, Ifitm3, H2‐K1, Vim, Bst2, Lag3, Cd74, Isg15, Gbp3, and Cxcl10." (PMID 38946585, 2024).
ductal carcinoma in situ (1 paper, 2014). "We therefore investigated this possibility using the GEO dataset GSE21422 containing BST-2 mRNA expression data from normal breast tissues and tumor tissues from ductal carcinoma in situ (DCIS) and invasive ductal carcinoma (IDC)." (PMID 25499888, 2014).
Ebola (1 paper, 2023). "The ectodomain and C-terminal GPI anchor are required for BST2 to bind directly to viral glycoproteins such as those of HIV-2 and Ebola." (PMID 37922253, 2023).
Enterovirus infection (1 paper, 2019). "Enterovirus infection can induce increased ATP1B3 levels that regulate the immune response by inducing the production of type I IFNs in RD muscle cell line and ATP1B3 protein can modulate HIV-1 restriction and NF-κB activation in a BST-2-dependent manner in Hela cells." (PMID 31331374, 2019).
hearing impairment (1 paper, 2026). A decreased magnitude of the sensory perception of sound. "In particular, the decline in SCs' migratory function mediated by BST2 exhibits a positive correlation with hearing impairment, which elucidates a novel mechanism underlying ARHL and identifies a potential therapeutic target for this condition." (PMID 41391004, 2026). "In future research, we plan to incorporate multiple in vivo and in vitro models, as well as human samples, to further investigate the mechanistic roles of BST2 and inflammatory processes in ARHL and other forms of hearing loss." (PMID 41391004, 2026).
HIVinfection (1 paper, 2020). "In a model of single round VSV-G/HIVinfection in vitro, as expected, BST-2 protein expression wasdownregulated on infected T cells in the absence of T0070907." (PMID 33089034, 2020).
kidney injury (1 paper, 2023). Trauma to the kidney. "Expression of ISGs (Mx1, Isg15, Isg20, Ifitm1, Bst2, and Oas1), and immune cell markers Lyz2 and Cd68 were markedly lower in 3TC mice with FA-induced kidney injury compared to controls." (PMID 36732547, 2023).
leukocytosis (1 paper, 2019). "While the pDCs did not repopulate in mice, the MDPs expanded in mice and developed lethal BPDCN with the same phenotype of CD11b−CD11cmid/+B220+Bst2+ following leukocytosis and thrombocytopenia." (PMID 30971697, 2019).
lung fibrosis (1 paper, 2022). "EGFR+ SSc fibroblasts also expressed higher levels of interferon inducible genes (IFI27, BST2), which have been shown to correlate with SSc disease severity, and IL6, a profibrotic cytokine whose inhibition slows SSc-associated lung fibrosis." (PMID 36490328, 2022).
MELAS (1 paper, 2023). "In IRF2 targets, which were significantly enriched in MELAS subjects, Polg mice, and Tfam± MEFs, USP18, TAP1, BST2, IFI35 were consistently increased." (PMID 37208779, 2023).
myopia (1 paper, 2025). "Macrophages in the myopia group upregulated proinflammatory Ifitm3/6, Apoc1, and Bst2-Siglech in the large intestine, proinflammatory ly6c1, Apoc1, and S100a in the liver, and ly6c1 and S100a in the kidney." (PMID 41330940, 2025).
Obesity (1 paper, 2022). Accumulation of substantial excess body fat. "BST2 was higher expressed in the visceral depot in APSCs from both non-obese women and women living with obesity." (PMID 36340033, 2022).
osteoporosis (1 paper, 2024). A condition of reduced bone mass, with decreased cortical thickness and a decrease in the number and size of the trabeculae of cancellous bone (but normal chemical composition), resulting in increased fracture incidence. "BST2 regulates BMP-2 pathway and therefore any negative effects will disrupt the osteogenic process and potentially cause osteoporosis." (PMID 39497989, 2024).
ovarian tumors (1 paper, 2025). "In vivo assessments revealed that BST2 augmentation modified the macrophage phenotypes within grafted ovarian tumors, with BST2 diminution reversing these effects." (PMID 41281378, 2025).
pancreatic ductal adenocarcinoma (1 paper, 2024). An infiltrating adenocarcinoma that arises from the epithelial cells of the pancreas. "In pancreatic ductal adenocarcinoma (PDAC), BST2+ macrophages induce CD8+ T cell exhaustion via activation by ERK/CXCL7, resulting in PDAC tumor growth." (PMID 39684750, 2024).
periodontitis (1 paper, 2024). An acute or chronic inflammatory process that affects the tissues that surround and support the teeth. "Additionally, C1QA exhibited a correlation with inflammation in geneCards, which implied that CENPK, CENPU and BST2 could feasibly manifest as factors linked to periodontitis." (PMID 38919957, 2024). "The enriched pathways in the PPI network were also immune-regulation related, which suggested to a certain extent that C1QA played a certain role in immune regulation in periodontitis, and BST2 was a more likely potential periodontitis regulator." (PMID 38919957, 2024). "BST2, CENPU and CENPK are the potential undiscovered genes that are related to the regulation of periodontitis." (PMID 38919957, 2024). "The identified biomarkers C1QA, CENPK, CENPU, BST2 and LINC01133 provided valuable insight into periodontitis pathology." (PMID 38919957, 2024).
Rotavirus infection (1 paper, 2021). Infection with any of the rotaviruses. "These partially shared DEGs included for example C-X-C Motif Chemokine Ligand 11 (CXCL11) and Bone Marrow Stromal Cell Antigen 2 (BST2, also called Tetherin), which was up-regulated in response to norovirus and astrovirus but not rotavirus infection." (PMID 34205050, 2021).
sarcoma (1 paper, 2025). A usually aggressive malignant neoplasm of the soft tissue or bone. "Also, human sarcoma-infiltrating NK cells expressed BST2, which has been observed to be upregulated in blood cancer cell lines exposed to NK cells." (PMID 41208961, 2025).
SARS-CoV infection (1 paper, 2022). "Utilizing infectious cDNA clones icSARS-CoV and icSARS-ORF7abΔCoV—which lacks the ORF7ab protein—it was shown that BST-2 restriction of SARS-CoV infection is highly dependent on N-linked glycosylation of the BST2 extracellular domain." (PMID 35631059, 2022).
Sepsis (1 paper, 2017). Sepsis is defined as life-threatening organ dysfunction caused by a dysregulated host response to infection. "To get further insight into the expansion of CD11chiCD4+ pDCs (that we had previously termed “CD4+ DCs”) in the bone marrow during sepsis, we investigated the expression of CD4 and MHC class II on CD11chi and CD11cint pDCs among total CD11c+Bst2+Ly6C+B220+ pDCs (for gating)." (PMID 29218051, 2017).
tumor (93 papers, 2008 to 2026). "BST2, an interferon-stimulated gene, is implicated in viral inhibition and tumor cell proliferation." (PMID 41751238, 2026). "Several high-scoring proteins, including ITGB8, LGR5, FZD7, HLA-E, ANGPTL2, and BST2 emerged as candidates potentially affected by protonation-linked perturbations in acidic tumor microenvironments." (PMID 42036641, 2026). "Functionally, BST2 promotes proliferation, epithelial-mesenchymal transition, anoikis resistance, and chemoresistance, whereas its loss sensitizes tumor cells to proteotoxic and metabolic stresses." (PMID 41595667, 2026). "Although a large number of immune cells that infiltrated the tumor microenvironment were associated with the high expression of BST2, determining the main type of immune cell that contributed to the interaction with cancer cells would be interesting." (PMID 36594082, 2023). "Of the six genes identified, IFI27, IFI6, IFITM1, ISG15, and BST2 have been reported to be associated with cancer cell proliferation and tumor growth." (PMID 35267998, 2022). "Our study identifies an underlying regulatory mechanism gone awry that activates BST2 in breast epithelial cells during tumorigenesis, and contributes to the functional hallmarks of cancer portrayed by tumor cells overexpressing this gene product." (PMID 23840623, 2013). "The role of BST2 in cell–cell interaction has also been implicated in tumor development." (PMID 39796009, 2024). "Notably, the expression levels of APOE, BGN, C1QB, and BST2 were found to correlate with cancer genomic atlas data, and were implicated in tumor immune infiltration." (PMID 39650066, 2024). "Loss of BST2 also affects the phenotype of tumor-associated macrophages." (PMID 35865015, 2022). "BST2, on the other hand, has mostly been associated with antiviral responses but might also tether tumor-derived EVs to LN LECs." (PMID 35892863, 2022). "BST2 has also been proposed as a tumor-associated antigen in some tumor cell lines." (PMID 35865015, 2022). "BST-2 expression in tumor tissues is positively associated with hosts’ survival." (PMID 25499888, 2014). "BST2 has emerged as a multifunctional molecule that bridges antiviral defense, membrane architecture, and tumor immunity." (PMID 41595667, 2026). "Beyond tumor cells, BST2 modulates the tumor microenvironment by promoting M2 macrophage infiltration, dendritic cell exhaustion, and natural killer (NK)-cell resistance, thereby contributing to immune evasion." (PMID 41595667, 2026). "In vivo xenograft experiments revealed that elevated BST2 expression not only accelerated EOC tumor growth but also skewed TAM polarization toward the M2 phenotype." (PMID 41281378, 2025). "These in vitro results were mirrored in vivo, where BST2 overexpression promoted xenograft tumor growth and knockdown had the opposite effect." (PMID 41281378, 2025). "Regarding pDCs, their ability to produce IFN-I can be disrupted by contact between immunoglobulin-like transcript 7 (ILT7) on pDCs and bone marrow stromal antigen 2 (BST2) on tumour cells." (PMID 35406451, 2022). "A gene correlated with IFN expression was BST2 which we found to be positively correlated with multiple immune checkpoint genes and negatively correlated with tumor purity, CD8+ T cells, and M2 type macrophages." (PMID 35865015, 2022). "Immunoglobulin-like transcript 7 (ILT7) recognizes bone marrow stromal cell antigen 2 (BST2), which is highly expressed on tumor cells, resulting in negative regulation of the interferon responses." (PMID 36303138, 2022). "Analysis of scRNA-seq TNBC data further supported the significant association between MUC1 and expression of IRDS genes encoding IRF7, BST2, IFI35 and IFITM1 in individual TNBC tumor cells." (PMID 35681561, 2022). "On the other hand, knockdown of Bst2 increased tumor latency and reduced tumor volume in E0771 and 4T1 models." (PMID 35651625, 2022).
tumor (continued). "Representative subclusters (Mφ_c1, c5, and c13) of these potential anti-tumor BST2+/MHC-II+ macrophages decreased and even disappeared when the tumor progressed to the late stage." (PMID 35316682, 2022). "Other studies have also demonstrated that inhibiting BST2 can achieve the effect of inhibiting tumor cell growth or inducing cell death." (PMID 35865015, 2022). "For example, there is a possibility that pDCs express different levels of molecules such as ILT7, which recognizes Bone Marrow Stromal Antigen 2 (BST2) that is expressed on tumor cell lines and primary carcinomas." (PMID 33953842, 2021). "It was also shown that tumor cells alone can modulate the gene expression profile of naïve MSCs, including IL-6, BST2, ADAMTS12, MX2, LOXL2 and GREM1." (PMID 34513701, 2021). "Three membrane-associated proteins, namely E-selectin, BST2, and HMMR were found to be upregulated in LECs after direct interaction with highly metastatic tumor cells." (PMID 31963450, 2020). "Accumulating studies have provided evidence that BST2 is involved in tumor progression in many cancer types, including breast cancer." (PMID 30655550, 2019). "BST2 was demonstrated to promote tumor survival, invasion and metastasis through a plethora of mechanisms." (PMID 30655550, 2019). "BST-2 employs its pro-tumor effects through the formation of BST-2:BST-2 dimers which ultimately promotes cell to cell and cell to matrix adhesion, cell motility, survival, and growth." (PMID 29523843, 2018). "Where positive, membranous and cytoplasmic BST-2 staining of invasive tumor cells was noted with varying levels of intensity." (PMID 30514852, 2018). "About 34% (27/79) of patients bear BST-2+ IBC; where BST-2 positivity was defined as tumors with BST-2 staining of 10% of tumor cells or higher." (PMID 30514852, 2018). "Competitive experimental pulmonary metastasis shows that silencing BST-2 reduces the numbers of viable circulating tumor cells (CTCs) and decreases the efficiency of lung colonization." (PMID 30514852, 2018). "To investigate relationships among BST2, the NF-κB pathway and anti-apoptotic factors downstream of NF-κB, we examined the protein levels of BST2, IκBα and Bcl-XL in tumor tissues from patients with NPC by immunohistochemistry (IHC) assay." (PMID 28617432, 2017). "The principle of this new model is that dimeric BST-2 allows interaction between cancer cells and the tumor microenvironment that promotes the survival, growth and metastasis of tumor cells." (PMID 28300825, 2017). "To this end, we randomly selected 117 patients who were newly diagnosed with locally advanced NPC and treated with radiotherapy plus cisplatin-based chemotherapy (at least 2 cycles), and examined BST2 expression by IHC in biopsy tumor specimens." (PMID 28617432, 2017). "The cellular mechanisms that control BST-2-mediated effect in tumor progression involve enhancement of cancer cell motility―migration/invasion." (PMID 29299143, 2017). "Correlation studies using meta analyses of various tumor datasets showed that BST‐2 levels are proportional to the aggressiveness of different cancers including breast 123, 129, brain 128, and oral cavity cancers." (PMID 27042298, 2016). "Our present study demonstrated the overexpression of BST2 in tumor cells of CRC tissues, which is correlated with poor prognosis of CRC patients." (PMID 26494939, 2015). "The CpG sites corresponding to probes 8 and 9 that are downstream and distal to BST-2 TSS were of significance to the triple-negative tumor subtype, as its methylation beta-value was lower compared to other subtypes." (PMID 25860442, 2015). "Nevertheless, RNAi-mediated downregulation of BST-2 increases the survival of tumor-bearing mice, suggesting therapeutic significance." (PMID 25860442, 2015). "Expression of BST-2 in E0771 cells had a tumor-enhancing effect similar to the one observed with the 4T1 cells." (PMID 25499888, 2014).